UBE2E3 (ubiquitin conjugating enzyme E2 E3)
Description:
Accepts ubiquitin from the E1 complex and catalyzes its covalent attachment to other proteins. In vitro catalyzes 'Lys-11'- and 'Lys-48'-, as well as 'Lys-63'-linked polyubiquitination. Participates in the regulation of transepithelial sodium transport in renal cells.
Synonyms: UBCH9; UbcM2
Tractability: PROTAC: ubiquitination databases record sites on it.
Gene: Protein-coding gene on chromosome 2 (180,967,248 to 181,076,585, forward strand). Ensembl gene ENSG00000170035.
Subcellular location: Nucleus; Cytoplasm
Pathways (Reactome):
Immune System: Antigen processing: Ubiquitination & Proteasome degradation
Metabolism of proteins: Synthesis of active ubiquitin: roles of E1 and E2 enzymes
Gene Ontology:
Molecular function: protein binding; ubiquitin conjugating enzyme activity; ubiquitin-protein transferase activity
Biological process: protein K11-linked ubiquitination; protein K48-linked ubiquitination; protein K63-linked ubiquitination; protein monoubiquitination; protein ubiquitination
Cellular component: cytosol; nucleoplasm; cytoplasm; nucleus
Genetic constraint (gnomAD): Loss-of-function variants: 2 observed, 15.18 expected, observed/expected ratio (o/e) 0.13, 90% interval 0.053 to 0.41. The upper end of that interval is the gene's LOEUF score, 0.41, which puts it in group 1 of 6, group 1 being the genes least tolerant of losing a copy. Missense variants: 63 observed, 188.08 expected, observed/expected ratio (o/e) 0.33, 90% interval 0.27 to 0.41. Synonymous variants: 60 observed, 66.44 expected, observed/expected ratio (o/e) 0.9, 90% interval 0.73 to 1.12.
Homologues: Orthologues: chimpanzee UBE2E3 (100% identical), dog UBE2E3 (100% identical), mouse Ube2e3 (100% identical), pig UBE2E3 (100% identical), rat Ube2e3 (100% identical), macaque UBE2E3 (99% identical), tropical clawed frog ube2e3 (99% identical), zebrafish ube2e3 (95% identical), guinea pig UBE2E3 (84% identical). Paralogues in human: UBE2E2 (85% identical), UBE2E1 (77% identical), UBE2D2 (46% identical), UBE2D3 (45% identical), UBE2D4 (45% identical), UBE2D1 (43% identical), UBE2Q2 (31% identical), UBE2Q1 (30% identical), UBE2L5 (26% identical), UBE2L3 (25% identical), UBE2L6 (25% identical), UBE2QL1 (16% identical).
Diseases named in the same sentence as UBE2E3 in open-access papers:
UBE2E3 is named in the same sentence as 11 diseases in open-access papers, as found by Europe PMC text mining. Sharing a sentence is not in itself a finding about the gene and the disease. The quoted sentences say what the papers report.
breast carcinoma (2 papers, 2024 to 2026). "Our studies showed that miR-379-5p mimics reduce UBE2E3 expression at both the mRNA and protein level in normal breast cells as well as breast cancer cell lines." (PMID 39621672, 2024). "In addition, by silencing UBE2E3, we were able to determine that UBE2E3 promotes cell viability and survival in breast cancer cells." (PMID 39621672, 2024). "This showed that UBE2E3 promotes cell viability, and suggests that suppression of UBE2E3 expression by miR-379-5p may restrain breast cancer cell numbers." (PMID 39621672, 2024). "We will note here that a correlation analysis of miR-379 and UBE2E3 RNAseq gene expression levels in TCGA Breast Cancer (BRCA) samples using the UCSC Xena platform does not reveal any significant correlation between the two." (PMID 39621672, 2024).
celiac disease (2 papers, 2019 to 2021). An autoimmune genetic disorder with an unknown pattern of inheritance that primarily affects the digestive tract. "As regards coeliac disease diagnosis above 7 years of age in the case–control analysis, rs653178 (at SH2B3/ATXN2), rs13010713 (at ITGA4/UBE2E3), rs13151961 (at IL2/IL21), rs11712165 (at CD80) and rs10936599 (at MYNN) showed an association." (PMID 33446885, 2021).
breast adenocarcinoma (1 paper, 2024). "To verify that UBE2E3 is a target, we transfected normal human epithelial mammary cells and breast adenocarcinoma cell lines with a miR-379-5p mimic." (PMID 39621672, 2024). "Next, we examined effects of the miR-379-5p mimic on UBE2E3 protein levels in AG11132 cells, as well as MCF7 and MDA-MB-231 breast adenocarcinoma cell lines." (PMID 39621672, 2024).
osteoporosis (1 paper, 2021). A condition of reduced bone mass, with decreased cortical thickness and a decrease in the number and size of the trabeculae of cancellous bone (but normal chemical composition), resulting in increased fracture incidence. "We used two gene expression profiles (GSE35956 and GSE35958) associated with osteoporosis and selected the promising gene Ubiquitin-conjugating enzyme E2 E3 (UBE2E3)." (PMID 34820159, 2021). "Since osteoporosis has a close relationship with age, we selected UBE2E3 as the promising gene that might be associated with osteoporosis." (PMID 34820159, 2021). "We used bioinformatics technology to explore and verify osteoporosis related hub genes, among which UBE2E3 decreased in old BMSCs compared with that in young BMSCs and was positively associated with osteogenesis related genes." (PMID 34820159, 2021). "Based on the bioinformatics analysis and in vitro experiments, we identified the promising gene UBE2E3 for osteoporosis, which regulated the senescence and osteogenic differentiation of BMSCs." (PMID 34820159, 2021). "UBE2E3 may be potentially involved in the pathogenesis of osteoporosis by regulating cellular senescence and osteogenic differentiation of BMSCs." (PMID 34820159, 2021). "In addition, we found that UBE2E3 significantly decreased in BMSCs of patients with osteoporosis from GSE35956 and GSE35958." (PMID 34820159, 2021). "In that case, UBE2E3 may be a significant target gene in the treatment of osteoporosis." (PMID 34820159, 2021).
post-traumatic stress disorder (1 paper, 2024). An anxiety disorder precipitated by an experience of intense fear or horror while exposed to a traumatic (especially life-threatening) event. "Intriguingly, an association has been found between post-traumatic stress disorder and UBE2E3 expression in neurons." (PMID 38391926, 2024).
cancer (4 papers, 2014 to 2024). A tumor composed of atypical neoplastic, often pleomorphic cells that invade other tissues. "Finally, to determine if the effect of miR-379-5p on UBE2E3 is related to cellular behaviors that play a role in cancer development, we measured cell viability by resazurin assay, cell proliferation by BrdU assay, and apoptosis by caspase 3/7 activation assay." (PMID 39621672, 2024).
tumor (3 papers, 2022 to 2024). "The studies in this paper have shown how reduction in miR-379-5p expression in tumors and increase in UBE2E3 expression may cooperate to promote tumor development." (PMID 39621672, 2024). "Intriguingly, we noticed the activity of the ubiquitin-mediated proteolysis pathway, as well as the expression of multiple ubiquitin-conjugating enzymes including UBE2S, UBE2E3 and UBE2C, were upregulated in tumor cells from solid samples." (PMID 36138435, 2022).
infection (1 paper, 2022). The state of being infected such as from the introduction of a foreign agent such as serum, vaccine, antigenic substance or organism. "The few proteins for which a fold-change >2 or <−2 was observed 48 h after infection are involved in apoptosis (SCARF1, PLSCR3), ubiquitination (UBE2E3, OTULIN), or the response to type I IFN (OAS2)." (PMID 35337059, 2022).
UBE2E3 also shares sentences with these, for which no sentence is quoted: mesothelioma (1 paper); Obesity (1); Testicular atrophy (1).